CASP8 (caspase 8)
Diseases named in the same sentence as CASP8 in open-access papers (continued):
Sharing a sentence is not in itself a finding about the gene and the disease.
glioblastoma (continued). "To clarify whether Caspase-8 expression and phosphorylation on Y380 may modulate glioblastoma cells metabolism, we performed bioenergetic analysis through Seahorse Bioscience technology." (PMID 41053176, 2025). "High endogenous phosphorylation levels on Tyr380 of Caspase-8 were observed in those contexts in which Src is aberrantly active, such as colon and hepatic tumors and glioblastoma, where Caspase-8 rewires its apoptotic and oncosuppressive function towards pro-tumoral functions." (PMID 37444381, 2023). "Bioymifi was the first DR5 activator reported in 2013, and it could bind directly to DR5 to activate the caspase 8-induced apoptosis signaling pathway, leading to human glioblastoma (T98G) cells apoptosis." (PMID 36034825, 2022). "However, even if the expression of TRAIL-R1 and TRAIL-R2 is increased in glioblastoma cells, resistance to TRAIL-induced apoptosis can be caused by low levels of caspase-8 and FADD." (PMID 34485282, 2021). "Furthermore, caspase-8 expression enhanced the resistance to temozolomide via NF-κB activation in glioblastoma cells." (PMID 34482382, 2021). "Thus, the interplay between caspase-8 and NFκB is essential for NFκB-dependent tumors (ovarian, breast, gastrointestinal cancer, and glioblastoma)." (PMID 33026575, 2021). "Importantly, genomic analyses of human glioblastomas have shown that caspase-8, an essential component of the DISC, is frequently inactivated by either gene mutations or promotor methylation." (PMID 31534206, 2019). "Furthermore, it has been shown that the Fas-FasR pathway is inhibited at the level of caspase-8 activation in glioblastoma patients, and that a lower caspase-8 expression is correlated with a poorer prognosis." (PMID 30486451, 2018). "Bioinformatic analysis of clinical data derived from glioblastoma patients identify a strong correlation between high levels of Caspase-8 expression and worse prognosis further confirming the central role of Caspase-8 expression both in the development and in the response to therapy." (PMID 30501030, 2018). "Interestingly, Caspase-8 expression in glioblastoma is often retained, and in particular Caspase-8 is upregulated in the mesenchymal subgroup." (PMID 30501030, 2018). "We have recently shown that in glioblastoma cell lines Caspase-8 expression sustains NF-κB nuclear accumulation and correlates with NF-κB transcriptional activation of several cytokines such ad IL-6, IL-8, VEGF (Vascular Endothelial Growth Factor), IL-1 and βα." (PMID 30501030, 2018). "Future studies will also clarify whether, strategies to target FLIP protein expression, to impair Caspase-8 phosphorylation on Tyr380, or to impinge on Caspase-10 expression may be beneficial in glioblastoma." (PMID 30501030, 2018). "In agreement with the central role of Caspase-8 in this pathway, several studies highlight that TRAIL sensitivity in glioblastoma is tightly dependent on the expression levels of Caspase-8 or on the expression levels or activity of the modulators of its apoptotic activation such as FLIP proteins." (PMID 30501030, 2018). "Future experiments will clarify whether Tyr380 phosphorylation may also play a role in the modulation of other Caspase-8 functions in glioblastoma." (PMID 30501030, 2018). "Importantly, this observation is in agreement with large-scale expression studies that revealed Caspase-8 upregulation in glioblastoma patients compared to normal tissue, in particular in the mesenchymal subtype." (PMID 30501030, 2018). "However, some cancers keep the gene for Caspase-8 switched on including glioblastoma, the most aggressive type of brain cancer in adults." (PMID 28594322, 2017). "In contrast, siRNA down regulation of gelatinase B/MMP-9 expression induces apoptosis in human glioblastoma cells in association with Fas death receptor-mediated caspase 3 and caspase 8 cleavage, implicating gelatinase B/MMP-9 in protecting glioblastoma cells against Fas ligand-mediated apoptosis." (PMID 24473089, 2014).
glioblastoma (continued). "Consequently, we reported an increase in the transcription and expression of the DISC complex components, including TNFR1, FADD and TRADD, leading to the activation of cleaved caspase 8 and ultimately resulting in caspase-dependent cell death of glioblastoma cells." (PMID 38212807, 2024). "Among the tumors in which Caspase-8 expression are upregulated, glioblastoma (GBM) shows ex novo synthesis of Caspase-8 protein." (PMID 37444381, 2023). "Intriguingly, other tumors, such as glioblastoma, preferentially retain Caspase-8 expression, and high levels of Caspase-8 expression may correlate with a worse prognosis, suggesting that in this context this protease loses its apoptotic activity and gains additional functions." (PMID 30501030, 2018). "Emerging evidence suggests that the retention of Caspase-8 in glioblastoma may interfere with the sensitivity to radio and chemotherapeutic approaches through multiple pathways, including the improvement of the DNA damage repair and the activation of NF-κB and cytokine production." (PMID 30501030, 2018). "We recently demonstrated that Caspase-8 promotes the proliferation and neoplastic transformation of glioblastoma (GBM) cell lines." (PMID 28594322, 2017). "Here, we discovered by in silico and in vitro experiments a strong impact of Caspase-8 expression on NRF2 expression and signaling in glioblastoma." (PMID 41053176, 2025). "Moreover, in glioblastoma, high doses of radiation may inhibit the activation of caspase-8, leading to the necrosome formation, and thus, necroptosis is executed, but in response to low-dose radiation, active caspase-8 induces apoptosis." (PMID 31122251, 2019). "Consistent with this possibility, we found that in a series of glioblastoma cells including LN428 cells treated with TRAIL, complete activation of caspase-8 and functional DISC formation were blocked." (PMID 31534206, 2019). "Glioblastoma patients with methylated MGMT were significantly younger than those whose tumor lacked methylation (P < 0.05) and an opposite was observed for CASP8 (P < 0.01)." (PMID 22672670, 2012). "In glioblastoma specimens gene methylation was observed as follows: MGMT in 51.3%, GATA6 in 68.4%, CD81 in 46.1%, DR4 in 41.3% and CASP8 in 56.8% of tumors." (PMID 22672670, 2012). "Analysis of the methylation status of two proapoptotic genes, CASP8 and DR4, in our study revealed that these genes were methylated in 56% and 41% of glioblastomas, respectively." (PMID 22672670, 2012). "High methylation frequency of tested genes shows heterogeneity of glioblastoma epigenome and the importance of MGMT, GATA6 and CASP8 genes methylation in glioblastoma patient outcome." (PMID 22672670, 2012). "Last, caspase-8, alone, was found to bind to the focal adhesion kinase (FAK) and calpain-2 Ca2+ dependent protease (CPN2), displaying pro-metastatic function properties in glioblastoma cell lines." (PMID 38534365, 2024). "We recently demonstrated that in glioblastoma cellular models, Caspase-8 phosphorylation, independent of its enzymatic activity, sustains NF-κB activation and translocation into the nucleus promoting the expression of its target inflammatory cytokines." (PMID 37444381, 2023). "After treatment with 50 μM enzalutamide for 24 h, activities of caspase-8 in both human U87 MG and U87 MG-R glioblastoma cells were not altered." (PMID 36235203, 2022). "There, genes with a higher expression in glioblastoma compared to astrocytoma were VEGFA, 4EBP1, CCL2, PLAU (uPA), CXCL8 (IL8), CXCL10 (IP10), CASP8, HGF, LIF, CD40, CDCp1, TNFRSF11B (OPG), CD274 (PD-L1), IL6, CXCL1, CCL20 (MIP3α), CCL8 (MCP2), CD244, MMP1, TNFRSF9, CXCL6, MMP10, FGF5)." (PMID 35301393, 2022). "Exposure of human TMZ-sensitive U87 MG glioblastoma cells to 50 μM enzalutamide for 24 and 48 h did not change the activity of caspase-8." (PMID 36235203, 2022).
glioblastoma (continued). "In contrast, exposure to 50 μM enzalutamide for 24, 48, and 72 h did not influence activity of caspase-8 in human drug-resistant glioblastoma cells." (PMID 36235203, 2022). "Thus, blocking autophagy-lysosomal degradation prevents cleaved caspase-8 from clearance and markedly augmented the synergism of KPNB1 inhibitor/TRAIL combination in glioblastoma cells." (PMID 30742128, 2019). "Moreover, we will discuss how the different functions of Caspase-8 may impinge on the therapeutic response and how the molecular mechanisms that modulate their switch-on and -off may be exploited to ameliorate the response of glioblastoma to chemotherapy and radiotherapy." (PMID 30501030, 2018). "We could show that Src promotes Caspase-8 phosphorylation on Tyr380 in U87MG and U251MG glioblastoma cell lines, and this event contributes to their neoplastic transformation and resistance to anoikis." (PMID 30501030, 2018). "When mice were injected with human glioblastoma cells with experimentally reduced levels of Caspase-8, the cells grew poorly and did not form as many new blood vessels as unaltered glioblastoma cells." (PMID 28594322, 2017). "However, human Caspase-8 expression is retained in some tumors, including glioblastoma (GBM), suggesting that it may support cancer growth in these contexts." (PMID 28594322, 2017). "Exposure of SW480 cells to bosenatn and/or FasL neither decreased the level of the short form of FLIP as previously shown for glioblastoma cells, nor modify caspase-8 expression." (PMID 12618891, 2003). "Indeed, transcriptomic analysis on U87-MG glioblastoma cells genetically silenced or not for Caspase-8 expression highlighted a significant reduction of NRF2 expression and activity in shC8 cells compared to control ones." (PMID 41053176, 2025). "In addition, RNA-seq experiments comparing the transcriptomic profile of glioblastoma cells genetically silenced or not for Caspase-8 expression, highlighted a role of Caspase-8 in the modulation of several signaling pathways." (PMID 41053176, 2025). "Interestingly, we recently observed that Caspase-8 phosphorylation on Tyr380 is necessary for the interaction of Caspase-8 with IKK proteins and NF-κB, promoting NF-κB nuclear localization and the release of inflammatory and angiogenetic factors in glioblastoma cells." (PMID 37444381, 2023). "Only NLRP1 in OV, CASP8 in pheochromocytoma/paraganglioma (PCPG), glioblastoma (GBM), etc., showed a positive correlation between methylation and gene expression (P<0.05)." (PMID 35795676, 2022). "It has been suggested that low levels of caspase-8 and FADD are related to apoptosis resistance via death inducers by TRAIL in glioma, since expression levels of the receptors TRAIL-R1 and TRAIL-R2 are increased in biopsy samples from astrocytoma and glioblastoma patients." (PMID 30486451, 2018). "Although no results on glioblastoma cellular models have been reported yet, this pathway is conserved in other cancer cell types, demonstrating that Caspase-8 contributes to the functionality of the DNA damage response and its loss therefore promotes genomic instability and tumor development." (PMID 30501030, 2018). "First, TRAIL-R2, but not TRAIL-R1, is the main TRAIL receptor expressed on glioblastoma cells and its activation may trigger caspase-8 cleavage and initiation of apoptosis." (PMID 24740347, 2014). "Various mechanisms operating in glioblastoma cells have been involved in TRAIL resistance of these cells: FLIP overexpression due to its stabilization mediated by PTEN loss; absent/low caspase-8 and/or TRAIL-R2 expression; impaired cell death signaling originated from TRAIL-R activation." (PMID 24740347, 2014). "Moreover, they indicated that the ardipusilloside I-induced apoptosis in glioblastoma cells depends on the enhanced expression of the FasL/Fas-signaling pathway and is independent of the activation of caspase-8." (PMID 24256941, 2013).
glioblastoma (continued). "Furthermore, a caspase-8 inhibitor has only a very modest effect on CLytA-DAAO-induced cell death in glioblastoma cell lines (data not shown), confirming that the intrinsic apoptosis pathway is the principal mechanism involved in CLytA-DAAO-induced cell death in glioblastoma." (PMID 33198289, 2020). "In addition, we demonstrated that BV6 primes glioblastoma cells in a RIP1-dependent manner for Temozolomide (TMZ), the first-line chemotherapeutic agent in the treatment of glioblastoma, since knockdown of RIP1 significantly reduced BV6- and TMZ-induced caspase-8 activation and apoptosis." (PMID 26575016, 2015).
gastric cancer (45 papers, 2012 to 2025). A primary or metastatic malignant neoplasm involving the stomach. "The authors found that the CASP8 -652 6N deletion allele decreased susceptibility to lung, colorectal, esophageal, breast, cervical, and gastric cancers." (PMID 28915630, 2017). "We then sought to further delineate the mechanisms which underlie the combined effects of gastric cancer cell SF-CM on apoptosis-related proteins (caspase-3, caspase-8, Bax, bcl-2)." (PMID 22520554, 2012). "The gastric cancer cells were treated with yamogenin for 5 and 24 h and the activity level of caspase-8 and -9 was estimated with luminometry." (PMID 38731847, 2024). "Another finding concerning BTZ is that it increased caspase-8, -9 and -3 activities in head and neck cancer cells and in gastric cancer cells." (PMID 38835345, 2024). "The results showed that DR5-CBL-b/c-CBL-TrAF2 complex inhibited the TRAIL-induced apoptosis of gastric cancer cells by promoting TRAF2-mediated caspase-8 polyubiquitination." (PMID 39130630, 2024). "Resveratrol induced apoptosis in gastric cancer cells via NF-κB down-regulation leading to a decrease in the level of anti-apoptotic factor Bcl-2 and an increase in apoptotic factors caspase-3 and caspase-8." (PMID 38689275, 2024). "We investigated that PLCG1, CASP5, CASP8 and NLRP3 displayed the highest mutation frequencies in gastric cancer specimens." (PMID 37595258, 2023). "It has been reported that activation of caspase-8 and caspase-3 is involved in the mechanism of apoptosis induction in gastric cancer." (PMID 37242548, 2023). "Firstly, Caspase-8-mediated apoptosis is dampened, supporting an anti-apoptotic pathway in gastric cancer cells." (PMID 37891577, 2023). "Epithelial gastric cells-derived IL-18 binds to IL-18R, that is overexpressed on the gastric cancer cell membrane, and inhibits Caspase-8-mediated apoptosis while promoting tumor proliferation." (PMID 37891577, 2023). "Decreased cell viability of gastric cancer cells by evodiamine treatment was mediated by activation of caspase-3, caspase-7, caspase-8, and caspase-9; cleavage of PARP; and subsequent induction of apoptosis." (PMID 36135210, 2022). "Flow cytometry was used to determine caspase-8 and caspase-9 activity in gastric cancer cells after 24 and 48 h of incubation with the tested compounds." (PMID 34770912, 2021). "Z-VAD-FMK inhibited the increases in cleaved PARP, cleaved caspase 3, cleaved caspase 8, and cleaved caspase 9 protein levels, indicating that Genipin enhances apoptosis in gastric cancer cells." (PMID 31351462, 2019). "Caspase-3, caspase-8, and Bax protein levels increased after 48 h of treatment with SF-CM from most gastric cancer cells, while bcl-2 protein levels decreased." (PMID 22520554, 2012). "Our study confirmed the HP-induced m6A methylation could sensitized gastric cancer to 5-FU with activation of caspase-8 and induced apoptosis and pyroptosis." (PMID 39744419, 2025). "Thus, BRD2 disrupts the homeostasis of the FLP/Caspase-8 homeostasis and regulates apoptosis and apoptosis in HP-positive gastric cancer cells." (PMID 39744419, 2025). "This is also the first report to show that BRD2 could regulate Caspase-8 to induce PANoptosis in gastric cancer." (PMID 39744419, 2025). "Also, c-Cbl can degrade caspase-8 by ubiquitination and then inhibit cell apoptosis in gastric cancer." (PMID 34141730, 2021). "We observed the highest percentage of AGS gastric cancer cells with active caspase-8 and caspase-9." (PMID 34770912, 2021). "Further studies confirmed that TRAIL (5 ng/ml), Bay (5 μM), or combined treatment promoted the expression of cleaved-caspase-8/3, but inhibited the expression of P-gp in drug-resistant gastric cancer cells SGC7901/DDP and BGC823/DDP (Fig. 3aiii, biii), as compared with normal cells." (PMID 29576621, 2018).
gastric cancer (continued). "The caspase 8 variation trend was consistent with its expression in gastric cancer model." (PMID 27275821, 2016). "However, this concept is not necessarily transferable to other cancer entities, since the CASP8 InsDel and DelDel genotypes were contrarily described as favorable prognostic indicators for gastric cancer patients." (PMID 27507139, 2016). "Additionally, some triterpenes demonstrated cytotoxicity in several cells such as colon and stomach cancer cells, inducing apoptosis via extrinsic and intrinsic pathways and activating caspase-8, -9, and -3, and HEp-2, HCT 116, MCF-7, A-549, and PC-3 cancer cells." (PMID 32102219, 2020). "DR5, CBL-b/c-CBL, and TRAF2 form the complexes in TRAIL-resistant gastric cancer cells that target CBL-b and c-CBL by inhibiting the interaction of TRAF2 with caspase-8 and subsequent caspase-8 multiubiquitination." (PMID 39130630, 2024). "IL-18 promotes the immune escape of gastric cancer cells by upregulating programmed cell death 1 (PD1) in NK cells, downregulating CD70 in tumor cells and inhibiting the CASP8-mediated apoptosis in gastric cancer cells." (PMID 37833958, 2023). "In related studies, we have shown that the chemotherapeutic agent, oxaliplatin, can sensitize gastric cancer cells to TRAIL by regulating components of the apototic/survival machinery such as caspase-3, caspase-8, Bax, and Bcl-2 protein expression." (PMID 24351824, 2013). "In this study, we found that FKB promoted the expression of caspase-3, caspase-7, caspase-8, and caspase-9, suggesting that FKB may accelerate the apoptosis of gastric cancer cells partly through the mitochondrial pathway." (PMID 35879950, 2022). "In gastric cancer cells, irigenin sensitizes TNF-related apoptosis-inducing ligand (TRAIL)-induced apoptosis by enhancing the expression of pro-apoptotic molecules in the cells, as evidenced by elevated expression of Bcl-2, Caspase-3, and Caspase-8, and in order to make TRAIL produce ROS." (PMID 36532767, 2022). "THD has cytotoxic effect on Gastric cancer (GC) cell lines NCI-N87 and AGS, inhibiting colony formation ability, and induces nuclear fragmentation and apoptosis in a caspase-dependent manner through downregulation of caspase-9, caspase-8, and caspase-3 precursors." (PMID 32923398, 2020). "Therefore, caspase-8 or caspase-9 inhibitor alone did not strongly affect apoptosis of AGS gastric cancer cells." (PMID 22963678, 2012). "Furthermore, after knockdown of USP47 by RNA interference, we analyzed in gastric cancer cell lines metabolic activity/viability in an MTT assay, and apoptotic cell death by Annexin V staining and poly(ADP-Ribose) polymerase (PARP)-1, caspase 3, and caspase 8 cleavage, respectively." (PMID 29786670, 2018). "However, extrinsic apoptosis proteins [Cle-Caspase 8, DR4, Fas, Fas ligand (FasL)] were not significantly altered, suggesting that Cos induced apoptosis via intrinsic (mitochondrial) pathway in gastric cancer cells." (PMID 34869312, 2021).